AKR1B10P1 (aldo-keto reductase family 1 member B10 pseudogene 1)
Gene: Processed pseudogene on chromosome 10 (67,750,284 to 67,751,225, forward strand). Ensembl gene ENSG00000213606.
Diseases named in the same sentence as AKR1B10P1 in open-access papers:
AKR1B10P1 is named in the same sentence as 3 diseases in open-access papers, as found by Europe PMC text mining. Sharing a sentence is not in itself a finding about the gene and the disease. The quoted sentences say what the papers report.
hepatocellular carcinoma (1 paper, 2020). A malignant tumor that arises from hepatocytes. "In our previous research on oncogene AKR1B10 in hepatocellular carcinoma (HCC), its pseudogene, AKR1B10P1, was preliminarily noticed being anomalistic transcribed, whereas whether AKR1B10P1 plays any specific function in HCC is poorly understood." (PMID 32924268, 2020).
tumor (4 papers, 2020 to 2022). "AKR1B10P1, an isoform pseudogene of oncogenic AKR1B10, is validated as a down-stream target degraded by tumor-suppressing miR-138, and there existed a positive feedback from AKR1B10P1, by which miR-138 interacts with AKR1B10P1 via a ceRNA approach in HCC." (PMID 36028503, 2022). "Further findings demonstrate that depletion of AKR1B10P1 in HCC Hep3B cells induced tumour suppression in vitro, impacting cell growth and mobility, and inducing cell apoptosis." (PMID 32924268, 2020). "Anomalous transcription of AKR1B10P1 significantly promotes HCC cell growth and enhances tumour metastasis through activating the epithelial‐mesenchymal transition (EMT)." (PMID 32924268, 2020).
AKR1B10P1 also shares sentences with these, for which no sentence is quoted: liver (1 paper).